CD24 (CD24 molecule)
Diseases named in the same sentence as CD24 in open-access papers (continued):
Sharing a sentence is not in itself a finding about the gene and the disease.
breast cancer (continued). "The primary human and xenograft breast cancer CD44-/CD24- cells were purified from human fresh TNBC tissue cells or MDA-MB-231 xenograft tissue cells by flow cytometry sorting and cultured in L15 medium for 7 and 21 (specifically for cells from xenograft tissue cells) days, respectively." (PMID 34318746, 2021). "In addition, the results indicate that activation of LIFR signaling in breast cancer cells in the existence of CAF-secreted LIF can induce Nanog and Oct4 expression and increase breast cancer stem cell markers CD24−/CD44+." (PMID 34947829, 2021). "In this regard, the frequency of CD44-/CD24- cells in tumor tissues could be a valuable predictor of standard therapeutic response in breast cancer patients." (PMID 34318746, 2021). "CD44 is a cell surface adhesion molecule that mediates cell‐cell and cell‐extracellular matrix (ECM) interactions by binding to hyaluronic acid (HA), whilst CD24 is a small sugar involved in the negative regulation of chemokine receptor CXCR4 protein activity in mediating breast cancer metastasis." (PMID 33305893, 2021). "Furthermore, breast cancer cells MCF7 (CD24+/CD44−) and MDA-MB-231 (CD24−/CD44+) were continuously exposed to exogenous LIF and analyzed for CD24/CD44 expression variations over time." (PMID 34947829, 2021). "In contrast, knocking down hRNase 1 by small hairpin RNA (shRNA; sh-R1#1 and sh-R1#2) in KPL4 HER2+ breast cancer cells which express high levels of hRNase 1 significantly reduced the sphere-forming ability, the population of CD24−/CD44+ cells, and the TIC frequency." (PMID 33986289, 2021). "The results may provide novel insights into the role of CD44-/CD24- tumor cells in delayed breast cancer metastasis and into the potential use of CD44-/CD24- cells as a biomarker to predict survival and metastasis in breast cancer patients." (PMID 34318746, 2021). "In addition, the distribution of circulating CD4 + CD25 + FOXP3+ Treg lymphocytes and CD19 + CD24 + CD38 + B lymphocytes significantly increased in breast cancer patients compared with healthy controls using blood samples." (PMID 33726701, 2021). "Our work reveals that glycosylation modulates the localization of CD24 in breast cancer cell lines." (PMID 34360932, 2021). "In addition, the TF, RUNX2, can promote CD44/CD24 breast cancer stem cell properties and breast cancer tumorigenesis through the EMT process." (PMID 34993131, 2021). "Accordingly, it is reasonable to hypothesize that the frequency of CD44-/CD24- cells in human tumor specimens may be useful in the prediction of delayed breast cancer metastasis." (PMID 34318746, 2021). "Cufi and colleagues were the first to demonstrate a link between autophagy and the maintenance of tumours, whereby autophagy promoted higher expression levels of CD44 and vimentin in BCSCs (CD44+CD24-/low cells) isolated from the JIMT-1 epithelial breast cancer cell line." (PMID 33799834, 2021). "Moreover, the expression levels of CD24 and E-cadherin in the breast cancer tissues were down-regulated compared with the normal tissues." (PMID 34932597, 2021). "Moreover, following 4, 6, and 10 days of CAF-CM exposure of breast cancer cells, the expression of CD24/CD44 cell surface markers was analyzed by flow cytometry." (PMID 34947829, 2021). "As CD24+Thy1+ mammary tumor cells from MMTV-Wnt1 mice have been reported to possess TIC properties, we first performed limiting dilution experiments to ask whether CD24+Thy1+ primary tumor cells from MTB;TetO-Wnt1;TTC;rYFP mice were enriched for TICs." (PMID 34088357, 2021). "After stratification of the training group of patients, based on their distant metastasis, the frequency of CD44-/CD24- cells in breast cancer tissues of patients with postoperative distant metastasis was significantly higher than those without distant metastasis (p<0.0001)." (PMID 34318746, 2021).
breast cancer (continued). "CD24 primarily resides at the plasma membrane, and is highly expressed in various cancers, such as glioma, small cell lung carcinoma, urothelial carcinoma, ovarian and breast cancer." (PMID 34360932, 2021). "Also, it highlights the differential contribution of the two sites of N-glycosylation in CD24 sorting and the different requirements among the different breast cancer cell lines." (PMID 34360932, 2021). "Hence, a higher frequency of CD44-/CD24- breast cancer cells, like higher frequency of CD44+/CD24- CSCs, was associated significantly with a shorter DFS in the training set of patients regardless of standard therapies." (PMID 34318746, 2021). "Therefore, we propose a new dynamic model of cell transition phenotype under drug stress which involves the translocation of intracellular CD24 that allows each breast cancer cell to convert into CD24+ cell." (PMID 34426608, 2021). "Furthermore, d16HER2+ mammary tumors exhibited a higher frequency of CD29high/CD24+/SCA1low cells, a peculiar population enriched in murine mammary stem cells, than their FL-HER2+ cell counterparts." (PMID 34638263, 2021). "Therefore, we tested the impact of the exogenous LIF, and it altered the morphology of breast cancer cells to a cancer stem-cell-like phenotype, which was explained by the enhanced expression levels of dedifferentiation markers CD24−/CD44+." (PMID 34947829, 2021). "Breast cancer stem cells identified by CD44+CD24− cells formed tumors into Nod/Scid mice." (PMID 33233552, 2020). "Furthermore, the IL-6/JAK/STAT3 pathway has been shown to be important for the proliferation of CD44+CD24− stem cell–like breast cancer cells." (PMID 32328465, 2020). "Similarly, Hong and colleagues found that FH535, another β-catenin/TCF inhibitor, significantly suppressed tumor sphere formation and the CD44+/CD24− BCSC subpopulation in mouse breast cancer cells." (PMID 32391382, 2020). "Therefore, we performed flow cytometry analysis to examine the CD44/CD24 population in four different kinds of breast cancer cells (BT-549, MDA-MB-231, Hs-578T, and MCF-7 cells) 3 to 5 days after CRISPRMAX-PKAs delivery." (PMID 33374889, 2020). "First, we analyzed by flow cytometry whether the percentage of MDA-MB-231 and MCF-7 breast cancer cells displaying the CD44+/CD24– phenotype was changed by HS2ST1 and HS3ST2 overexpression." (PMID 33102470, 2020). "In basal/HER2+ breast cancer cell lines, Menendez and colleagues showed that EMT-associated transcription factors (Snail2 and Slug) enhance resistance to trastuzumab via inducing a BCSC phenotype (CD44+CD24−/low)." (PMID 32391382, 2020). "Combined, these data indicate that the majority of CTCs found in metastatic breast cancer patients maintain a stem-like (CD44+/CD24−) state, while staying mitotically inactive; whereas a smaller sub-population of CTCs are of an epithelial (PanCK+) phenotype, with a higher proliferative index." (PMID 32575420, 2020). "Cells with high CD44 but low CD24 expression (CD44high/CD24−/low) and high aldehyde dehydrogenase activity (ALDHbr) are widely considered to be drivers of metastasis, therapy resistance and tumor recurrence in breast cancer." (PMID 32423137, 2020). "ALDH1 and CD24 are widely used CSC markers in breast cancer." (PMID 32909943, 2020). "For example, CD24 is seen as a strong and independent molecular marker for the prognosis of ovarian cancer; it is also related to the growth and metastasis of breast cancer and may be related to the occurrence and development of pancreatic cancer." (PMID 32765491, 2020). "Indeed, a high CD44/CD24 ratio in breast cancer has been shown as an important breast cancer prognosis predictor and also to be enriched in circulating tumor cells and in distant metastases, such as in liver, bone, and lung." (PMID 33182375, 2020). "We thus further examined if emodin could affect the progenitor population in breast cancer cells using the markers CD24, CD49f and CD61." (PMID 32724475, 2020).
breast cancer (continued). "It was previously shown that the cell fraction with the CD44+/CD24-/Lin- phenotype in breast cancer patient tissues could recapitulate tumor burden in mice." (PMID 33488948, 2020). "The CD44+/CD24- population of breast cancer cells was assayed under machilin D treatment." (PMID 32033472, 2020). "We hypothesize that MET preferentially kills breast cancer initiating CD44+/CD24–/low cell subpopulation, leading to increased cell death." (PMID 31877620, 2019). "Whether ALDH-positive sorted cells indeed resemble a pure CSC population is not clear because there are various CSC markers, such as CD44 +/CD24 –, which are also known as indicators of CSCs in breast cancer." (PMID 30845764, 2019). "CD24 is broadly over-expressed on many types of tumor tissues and indicates a correlation between its expression and metastasis and points at an active role for CD24 in this process in lung cancer, breast cancer and prostatic cancer." (PMID 31534632, 2019). "Co-expression of CD44 and CD24 is frequently observed in basal/epithelial breast cancer cells and CD44+/CD24+ cells have shown to be more invasive and tumorigenic than CD44+/CD24neg cells and possess stemness characteristics of self-renewal and differentiation in multiple cancer types." (PMID 31217901, 2019). "Our previous studies show that ESA+CD44+CD24-/low breast cancer cells have stem-like cell characteristics and found that BCSCs on the conventional chemotherapy drug docetaxel, endocrine therapy drugs such as letrozole and targeted therapy trastuzumab, have a certain resistance." (PMID 30906504, 2019). "We also found that reconstitution of BRCA1 resulted in significant increase of the breast cancer cell population expressing high levels of the differentiation-associated CD24 cell surface protein without significantly affect CD24 mRNA levels." (PMID 31273285, 2019). "Moreover, CD24−/CD44+ stem-like cells can be generated from CD24+/CD44− cells after oncogenic Ras pathway activation in breast cancer stem cells (BCSCs)." (PMID 31614769, 2019). "In addition, this nanosensing technique is able to quantify exosomes with different surface biomarker expressions and has revealed that exosomes secreted from MCF-7 breast cancer cells have a higher CD24 expression compared to CD63 and CD81." (PMID 36133621, 2019). "Therefore, understanding the changes in the expression patterns of CD44 and CD24 in breast cancer after chemotherapy treatment is important for greater understanding of the clinicopathological properties of breast cancer." (PMID 31357721, 2019). "First, the breast carcinoma cell lines were characterized asCD44+/CD24-/low." (PMID 31384244, 2019). "An example consistent with the acquisition of an invasive phenotype upon MG stress is the up-regulation of CD24, a mucin-like adhesion molecule that enhances the metastatic potential of malignant cells and is shown to be a marker of poor prognosis in breast carcinomas." (PMID 30674353, 2019). "In addition, the HER2-STAT3 network has been shown to contribute to the aggressive phenotype of breast cancer stem cells, and the JAK2/STAT3 signaling pathway is required for the growth of CD44+CD24− stem cell-like breast cancer cells in human tumors." (PMID 29636641, 2018). "Moreover, evidence from a more recent study indicates that CD24 status has little bearing on tumourigenic potential in breast cancer and that CD24−/low status can in fact reduce tumour initiation in some murine models." (PMID 30377878, 2018). "Furthermore, some markers, such as E-cadherin, CD44 and CD24, which characterize the metastatic potential of human breast cancer cells, have been related to the molecular subtypes." (PMID 29632639, 2018). "OCT4med/low, CD44hi, CD24+ hierarchy of breast cancer cells have been reported recently." (PMID 30121075, 2018). "In addition, the expression levels of CD24 mRNA decreased in all breast cancer cells after stimulation with the same concentration of E2." (PMID 30179299, 2018).
breast cancer (continued). "We found more tumor cells with CD44+/CD24-/low phenotype could be detected in ER-positive and AR-positive breast cancers." (PMID 29423076, 2018). "However, the expression of CD24 was a significant poor prognostic factor in ER-positive early breast cancer treated with adjuvant tamoxifen." (PMID 29416796, 2018). "CD44+CD24- subpopulation has been regarded as a marker of CSCs in breast cancer cells." (PMID 29298343, 2018). "Therefore, we analysed CD44 and CD24 expression in breast cancer cells treated with different concentrations of E2 using real‐time PCR." (PMID 30179299, 2018). "This study aimed to explore whether IBC influences resistance of breast cancer cells to paclitaxel by regulating CD44/CD24 expression." (PMID 30179299, 2018). "Furthermore, RNA sequencing data revealed that migratory TICs have a gene expression signature distinct from currently used markers in breast cancer (ALDHbr and CD24−/low/CD44+), allowing us to investigate new molecular regulators of TICs." (PMID 29321615, 2018). "To test the hypothesis, we first compared the expression of KLF4, ALDH1A1, ALDH1A3, CD44, and CD24 in human breast cancer samples available in TCGA database." (PMID 30038266, 2018). "In this study, the CD24-positivity rate (13%) was lower than that in previous data (46~85%) from breast cancer studies including more than 100 samples, which may be explained in part by the limitations of IHC assay itself." (PMID 29416796, 2018). "Recently, a specific role of IR has been hypothesized in breast cancer progression through a novel mechanism involving CD24, a common cell surface marker for breast cancer stem cells, linked to IR for promoting tumor growth." (PMID 30453495, 2018). "A DNA microarray analysis identified that RNA interference of CD24, the breast cancer stem cells (BCSC) marker, could increase the expression of STAT1, which enhanced invasiveness and superior tumorigenicity." (PMID 28422733, 2017). "The results of the present study suggest that breast cancer patients with CD24 cell surface expressing cancer cells may also benefit from anti-ATF5 therapy." (PMID 28785242, 2017). "Breast cancer cells undergoing epithelial to mesenchymal transition (EMT) acquire a CD44+/CD24-/ALDH1+ cancer stem cell-like phenotype characterized by an increased capacity for tumor self-renewal, intrinsic drug resistance and high proclivity to develop distant metastases." (PMID 29207686, 2017). "To determine whether tumors containing drug-resistant breast cancer cells and/or increased CD44high/CD24-/low fractions possess greater tumor-initiating potential, we performed secondary transplantation." (PMID 28703802, 2017). "Similarly, the CSC population as defined by the cell surface markers CD44+/CD24- was significantly increased in both breast cancer cell lines by leptin." (PMID 28542577, 2017). "Moreover, silencing PRDM14 reduced the expression of CD44, which imparts cancer stemness, and STAT3, which is required for growth of CD44+CD24– stem cell-like breast cancer cells." (PMID 28423353, 2017). "Our results indicate that bone-derived osteopontin promotes the migration, tumorsphere-forming ability and colony-forming ability of whole population and ALDHhiCD44+CD24- breast cancer cells in bone marrow-conditioned media (an ex vivo representation of the bone microenvironment) (p≤0.05)." (PMID 28498874, 2017). "As reduced doxo resistance in CD44+/CD24- breast cancer cells is evidenced by suppression of CD44, we analyzed mRNA and protein levels for CD44; the result reveals MCF7/ADR cells with ∼150- and 16-fold higher levels of mRNA and protein, respectively, than in MCF7." (PMID 29050299, 2017). "Previous reports indicate that CD24 is involved in EMT-MET transitions in breast cancer cells." (PMID 28418843, 2017). "Importantly, CD24 was reported to induce the recruitment of integrin-β1 to lipid rafts and activate integrins-α3β1 and α4β1 in breast cancer cells, thereby leading to an increased motility of the cells." (PMID 28785242, 2017).
breast cancer (continued). "The CD44+/CD24–/ALDH+ phenotype is thought to increase tumourigenicity of breast cancer cells." (PMID 28707729, 2017). "Although several recent studies suggested CD24 expression could serve as a marker for adverse prognosis in certain tumors, low surface expression seems to enhance aggressiveness in breast cancer TICs." (PMID 28052035, 2017). "In fact, CD44−/CD24+ is a marker of poor prognosis in early invasive breast cancer." (PMID 28929082, 2017). "The Notch intracellular domain is released upon receptor activation and acts as a transcriptional cofactor to promote stemness, therefore we examined the levels of Notch1 receptor domains in the CD24+CD29hi stem cell-enriched population from PyMT-Ccr7WT and PyMT-Ccr7−/− murine mammary tumors." (PMID 28137279, 2017). "Increased efficiency of mammosphere formation and increased expression of the surface protein CD24 add further evidence in favor of the hypothesis that the MCF-7 breast cancer cells acquire stem cell-like properties as an early response to endocrine therapy." (PMID 28929082, 2017). "CD24 has been shown to enhance DNA damage induced apoptosis in breast cancers." (PMID 28373842, 2017). "Another cell surface marker is the single-chain sialoglycoprotein CD24, which is also associated with cancer stem cell characteristics in colorectal and pancreatic cancer, while head and neck cancer cells and breast cancer cells with CD44+CD24−/low expression are highly tumorigenic." (PMID 28837080, 2017). "We further investigated whether CD44/CD24 ratio was also correlated with the tumorigenesis of breast cancer cells by comparing the tumorigenicity of the four subtypes of cell lines in the xenotransplanted models." (PMID 29062075, 2017). "In the current study, we tested the hypothesis that these ALDHhiCD44+CD24- breast cancer cells interact with factors in the bone secondary organ microenvironment to facilitate metastasis." (PMID 28498874, 2017). "Recently, a study of patients with breast cancer detected glypican-1- and CD24-positive exosomes in patient serum samples, which may be used as biomarkers of breast cancer." (PMID 28659795, 2017). "In addition, epithelial mesenchymal transition (EMT) inducers can induce breast cancer cells to breast CSCs enriched with the CD44+/CD24- configuration." (PMID 29050299, 2017). "CD24 expression is also suggested to be a candidate marker for prognosis in breast cancer." (PMID 28418843, 2017). "Indeed, scanning electron microscopy showed CD44+CD24-/low breast cancer cells at the tumor invasive protrusions." (PMID 28052035, 2017). "Taken together these findings suggest that CD24 cell surface expression may serve as a valuable biomarker in order to identify mammary tumors that will positively respond to targeted IGF1R therapies." (PMID 27179633, 2016). "Furthermore, the chemo-tolerant subpopulation in both basal-like and luminal breast cancer cell lines co-express both an epithelial marker CD24 and a mesenchymal marker CD44, indicating its hybrid E/M status." (PMID 27008704, 2016). "High levels of CD44 and low levels of CD24 induce stem-like activities in breast cancer cells." (PMID 27713506, 2016). "Furthermore, our recent results, demonstrated that the CD24+ subset is highly tumorigenic; these cells formed rapidly growing mammary tumors and metastatic lesions compared to their CD24- counterparts." (PMID 27179633, 2016). "In breast cancer, EMT has been associated with CSCs characteristics including self-renewal ability and the expression of stem cell-associated cell subpopulation CD44+/CD24–/low." (PMID 27842518, 2016). "Thus, MMTV-PyMT breast cancer cells with the marker profile CD24+CD90+ show high tumorigenicity both in vitro and in vivo, while cells single- or double-negative for these markers do not." (PMID 27542270, 2016). "Moreover, we demonstrate that IGF1R-KD abolished both CD24+ cells capacity to form mammary tumors and lung metastatic lesions." (PMID 27179633, 2016).